BCL2 (BCL2 apoptosis regulator)
Diseases named in the same sentence as BCL2 in open-access papers (continued):
Sharing a sentence is not in itself a finding about the gene and the disease.
B-cell lymphoma (continued). "Endogenous expression of Bcl2 is not required for the development of Eμ-myc induced B-cell lymphoma, but it is needed to maintain mature B cells in healthy mice." (PMID 25680182, 2015). "Results from an incisional biopsy revealed a low-grade B-cell lymphoma (CD20+, CD43+, bcl2+, CD3-)." (PMID 23822827, 2013). "Incisional conjunctival biopsy results revealed a B-cell lymphoma (CD20+, CD43+, bcl2+, CD3-)." (PMID 23822827, 2013). "The data suggest that this mutation is not universally present in all germinal center-phenotype B cell lymphoma subtypes but appears to correlate with BCL2 status." (PMID 22194861, 2011). "In cases where high-grade cytology, high MYC (>40%) and BCL2 (>50%) expression, and the GCB phenotype are present, FISH analysis is recommended to assess for MYC and BCL2 rearrangements, which define high-grade B-cell lymphoma with MYC/BCL2 rearrangements, according to the 2022 WHO classification." (PMID 40881873, 2025). "Clear associations between phenotypes and genetic subtypes (e.g., MCD with extranodal sites or EZB-MYC and high-grade B-cell lymphoma (HGBCL)/DLBCL with MYC and BCL2 double hits) suggest that these differences may be related to the inherent heterogeneity of DLBCL and the selection of cohorts." (PMID 40067847, 2025). "The overexpression of Myc (≥ 40%) and Bcl2 (≥ 50%) protein by IHC in the absence of FISH identified translocations is usually associated with the ABC phenotype and identifies the so‐called double expressor B‐cell lymphoma (DEL)." (PMID 41185089, 2025). "Aggressive B-cell lymphomas with the genetic rearrangements of MYC, BCL2 and BCL6 may show either a blastoid morphology or an intermediate morphology between Burkitt lymphoma (BL) and DLBCL or, in half of cases, may be morphologically indistinguishable from DLBCL, NOS." (PMID 39684922, 2024). "Moreover, dysregulated BCL2 is a hallmark of more aggressive subsets of DLBCL, such as those that have both BCL2 and MYC rearrangements (originally called double-hit DLBCL), now classified as DLBCL high-grade B-cell lymphoma (HGBL), which are typically GCB subtype." (PMID 38893249, 2024). "Taken together, SC-1 carries three major rearrangements resulting in the gene fusions IGH::BCL2, IGH::MYC, and MBNL1::BCL6 which were characterized cytogenetically, genomically, and at the transcript level, thus, representing an exceptionally well characterized triple-hit B-cell lymphoma cell line." (PMID 37371852, 2023). "However, the negative TdT and expression of BCL6 in a subset of malignant cells raise the possibility of a high grade B-cell lymphoma with MYC and BCL2 rearrangements or a lymphoblastic transformation of follicular lymphoma, although there is no clinical evidence to support these diagnoses." (PMID 38175445, 2023). "High-grade B-cell lymphoma (HGBL) with MYC and Bcl-2 and/or Bcl-6 rearrangements is an aggressive mature B-cell lymphoma that harbours a MYC rearrangement at chromosome 8q24 and a rearrangement in Bcl-2 (at chromosome 18q21) and/or in Bcl-6(at chromosome 3q27)." (PMID 36618391, 2022). "A biopsy of the right mammary gland tumor was performed, showing CD20 (+), CD21 (-), bcl-2 (+), CD10 (+), CD30(-), bcl-6 (+), MUM-1 (+), C-myc (70%+), CD19 (+), TDT (-), MPO (-), Ki-67 (+90%), MYC, and BLC2 rearrangements; a pathological diagnosis of high-grade, double-hit B-cell lymphoma was made." (PMID 36032118, 2022). "Special emphasis was laid on this group of aggressive B-cell lymphomas in recognition of its complicated classification due to the concurrence of features of both Burkitt lymphoma (BL) and diffuse large B-cell lymphoma (DLBCL) including cytogenetic aberrations affecting MYC, BCL2 and/or BCL6." (PMID 33672644, 2021). "Interestingly, such interaction was only reported in primary cells derived from patients with B-cell lymphoma overexpressing BCL2 but not in noncancerous tissue." (PMID 31027363, 2019).
B-cell lymphoma (continued). "Although the belief in the importance of BCL-2 in human B cell lymphomas is firmly embedded, two different transgenic mice generated ~30 years ago revealed that Bcl-2 is not a driver of B cell lymphoma, but increased levels in B cells did lead to their accumulation." (PMID 30671383, 2018). "As BCL2 rearrangement is the one of the two “hits” in double-hit lymphoma, acquisition of c-MYC rearrangement during disease progression leads to histologic transformation to high-grade B-cell lymphoma/DHL and rarely plasmablastic lymphoma or blastoid transformation of FL/B-lymphoblastic lymphoma." (PMID 28379189, 2017). "This study raises the hypothesis that a subset of low-grade B cell lymphomas with a follicular growth pattern but without a BCL2 translocation actually represents NMZL." (PMID 26949422, 2016). "Unlike other aggressive B-cell lymphomas, BCL2 translocation may not occur in MCL, which indicates that BCL2 and CCND1 translocations might be mutually exclusive." (PMID 26517511, 2015). "It has been shown that bcl-2 protein plays an important role in the etiopathogenesis of some inflammatory autoimmune diseases, as well as hematopoietic malignancies, such as B cell lymphoma, in acute promyelocytic leukaemia, and non-hematopoietic malignancies, such as pancreatic beta-cell cancer." (PMID 24834112, 2014). "Within the group of B cell NHL (32 cases), 24 cases (75%) were diffuse large B-cell lymphoma (DLBCL) showing positive reaction to CD45, CD20, CD19 and large FSc, 2 cases (6.25%) were follicular lymphoma (FL) showing positive reaction to CD45, CD20, CD19, CD10, anti-BCL-2 and small to medium FSc." (PMID 18986555, 2008). "However, whereas in this model tumor development was associated with high BCL2 protein expression, our model generated exclusively BCL2 negative B cell lymphomas restricted to a specific window of differentiation, with a homogeneous transitional phenotype, all of high grade." (PMID 16563162, 2006). "FISH analysis of an aggressive B-cell lymphoma revealed an atypical BCL6 rearrangement with a 1G1F signal pattern, no BCL2 rearrangements, and no IGH::BCL2 fusion." (PMID 41010038, 2025). "Three (4%) patients harbored MYC and BCL6 rearrangements, while none exhibited high-grade B-cell lymphoma with MYC and BCL2 and/or BCL6 rearrangements." (PMID 40715072, 2025). "BCL2 and/or MYC rearrangements are absent and aggressive B-cell lymphomas with IRF4 rearrangement, harboring also MYC and/or BCL2 rearrangements, are excluded from this entity." (PMID 39684922, 2024). "All four of these cases with variant MYC FISH results also had BCL2 rearrangements, raising the possibility of high-grade B-cell lymphoma with MYC and BCL2 rearrangements, without a definitive diagnosis." (PMID 38903717, 2024). "All B-cell lymphoma patients had CD20 staining, 4 (80%) had CD43 and Bcl2, 2 (40%) had CD3 and CD23 staining, while none of the patients had CD10 and Cyclin D1 staining." (PMID 38301095, 2023). "High-grade B-cell lymphoma, NOS includes blastoid-appearing large B-cell lymphomas and cases lacking MYC and BCL2 or BCL6 translocations." (PMID 31484540, 2019). "Immunohistochemical stain revealed that tumor cells were diffusely positive for CD20, CD79a, bcl-2, and negative for CD3, CD5, CD10, cyclin D1 and bcl-6, which excludes the possibility of low grade B-cell lymphoma other than EMZL." (PMID 26111022, 2015). "Western blot analysis from all B-cell lymphoma cell lines showed that BRD4, Myc and Bcl-2 protein expression was not altered following I-BET762 treatment over time." (PMID 26658189, 2015). "To confirm the presence of MYC and BCL-2 rearrangements in the high-grade B-cell lymphoma, we performed FISH for myc and Bcl-2 genes, which yielded negative results, confirming that the patient did not have high-grade B-cell lymphoma." (PMID 41445799, 2025).
B-cell lymphoma (continued). "However, the 2022 World Health Organization (WHO) and International Consensus Classification (ICC) recommendations re-categorized MYC/BCL6 as “DLBCL, not otherwise specified” and MYC/BCL2 and MYC/BLC2/BCL6 as “DLBCL/high-grade B-cell lymphoma-MYC/BCL2”." (PMID 39696503, 2024). "In summary, overexpression of H3K27m3 can serve as a new, BCL2 independent marker in the differential diagnosis of FL and PCFCL, but not PTFL, to FH, while being not of help in the differential diagnosis of FL to other B cell lymphomas." (PMID 35661922, 2022). "In these studies, the histology-related inclusion criteria were different; in general, the studies included high-grade B-cell lymphoma (HGBCL) with or without translocations of MYC and BCL2 and/or BCL6 (double/triple-hit lymphoma) and transformed follicular lymphoma (tFL)." (PMID 36561713, 2022). "In conclusion, the results of our study confirm that R-CHOP is not an appropriate therapeutic choice for “high-grade B-cell lymphoma with MYC and BCL2/BCL6 rearrangements”, and that intensive regimens or DA-EPOCH-R should be preferred, especially for younger patients." (PMID 31976479, 2019). "Although high-grade B-cell lymphoma (HGBCL) prevalence showed no significant racial differences (p = 0.16), the Asian group exhibited a higher proportion of aggressive HGBCL with concurrent IGH::MYC and IGH::BCL2 fusions compared with the White group (p = 0.076)." (PMID 41301875, 2025). "Moreover, the cells were found to be positive for CD20, BCL-2, BCL-6 and IRF-4 (Mum-1) and be negative for CD10 and CD5 by Immunofluorescence, which was similar to the immunophenotypic profiles of the majority of HBsAg-positive B-cell NHL patients." (PMID 31120924, 2019). "In conclusion, B-cell lymphomas involving WR presented with a wide age range, male predominance, high rate of the localized clinical stage, a favorable outcome despite the high-grade histopathology, high rate of GCB phenotype, and more frequency of BCL2 expression lacking IGH/BCL2 rearrangement." (PMID 28086220, 2017).
acute myeloid leukemia (394 papers, 2011 to 2026). Acute myeloid leukemia (AML) is a group of neoplasms arising from precursor cells committed to the myeloid cell-line differentiation. "The anti-apoptotic protein B-cell lymphoma 2 (BCL-2) is highly expressed in leukemia stem cells and is linked to chemotherapy resistance and poor prognosis in acute myeloid leukemia patients." (PMID 40079007, 2025). "Bimiralisib has also been shown to have efficacy in combination with BCL2 (B-cell lymphoma 2) inhibitor venetoclax in acute myeloid leukemia (AML) with IDH2, NPM1, and FLT3 mutations in preclinical studies." (PMID 38396649, 2024). "Elevated levels of BCL2 protein in acute myeloid leukemia cells are associated with poor responses to chemotherapy." (PMID 37754227, 2023). "In this preclinical study, we assessed the HSP90 inhibitor PU-H71 in combination with the MCL1 inhibitor S63845 or the BCL2 inhibitor venetoclax in the treatment of acute myeloid leukemia and investigated the associated biomarkers of response." (PMID 37754227, 2023). "Preclinically, enasidenib and azacitidine (ENA + AZA) synergistically enhance cell differentiation, and venetoclax (VEN), a small molecule Bcl2 inhibitor (i) is particularly effective in IDH2 mutated acute myeloid leukemia (IDH2mutAML)." (PMID 35078972, 2022). "In this case-control study, the expression of genes encoding Nrf2, Keap1, Bcl2, Bcl- XL and Bax in 40 acute myeloid leukemia (AML) patients were compared with 40 normal individuals in the Iranian population." (PMID 34400968, 2021). "In vivo, single-agent INCB053914 inhibited Bcl-2–associated death promoter protein phosphorylation and dose-dependently inhibited tumor growth in acute myeloid leukemia and multiple myeloma xenografts." (PMID 29927999, 2018). "Bcl-2 antagonist ABT-199 has been shown to cause on-target cell death in acute myeloid leukemia, and significantly enhances imatinib-induced cell death in chronic myeloid leukemia." (PMID 27083050, 2016). "In acute myeloid leukemia (AML) quiescence and low oxidative state, linked to BCL2 mitochondrial regulation, endow leukemic stem cells (LSC) with treatment-resistance." (PMID 27669008, 2016). "Consistently, Bcl-2 protein expression was associated with drug efficacy in acute myeloid leukemia (AML)." (PMID 26392332, 2015). "Venetoclax is a selective BCL-2 inhibitor that has transformed the treatment landscape for elderly and unfit patients with acute myeloid leukemia (AML)." (PMID 41929632, 2026). "Venetoclax (VEN) was developed as a BH3 mimetic that selectively inhibits BCL2 and has demonstrated potential in various cancers, including breast cancer and colorectal cancer, as well as acute myeloid leukemia." (PMID 41596562, 2026). "FA-HP-β-CyD also exhibited antileukemic activity in acute myeloid leukemia cells via autophagic cell death and showed synergistic activity with venetoclax, a BCL-2 inhibitor." (PMID 41596562, 2026). "Venetoclax has a high affinity for the BH3 binding domain of Bcl-2, It inhibits the overexpression of Bcl-2 in acute myeloid leukemia (AML) cells, promoting apoptosis and inhibiting cell proliferation." (PMID 40861456, 2025). "In this context, YBX1 forms ribonucleoprotein complexes with IGF2BPs on m6A -modified transcripts, stabilizing key oncogenic mRNAs such as MYC and BCL2 in acute myeloid leukemia (AML)." (PMID 41346602, 2025).
acute myeloid leukemia (continued). "OPA1 participates in resistance against the tyrosine kinase inhibitor gefitinib in lung adenocarcinoma, the Bcl-2 antagonist Venetoclax in acute myeloid leukemias, and in the development of residual disease following standard-of-care treatment for TNBC." (PMID 40691145, 2025). "Venetoclax is approved for the treatment of acute myeloid leukemia and chronic lymphocytic leukemia, in which BCL-2 overexpression plays a critical role in disease progression." (PMID 40573290, 2025). "Simultaneously, venetoclax (ABT-199), a selective Bcl-2 inhibitor, had been approved for the treatment of hematologic malignancies, including acute myeloid leukemia." (PMID 40707448, 2025). "Despite advances with novel targeted agents (e.g., BCL-2 or IDH inhibitors) combined with chemotherapy for acute myeloid leukemia (AML), drug resistance persists." (PMID 41294812, 2025). "In a clinical study in 57 newly diagnosed acute myeloid leukemias, low BCL-2 expression levels predicted longer Progression-Free Survival (PFS) (p = 0.02) and longer overall survival (p = 0.06)." (PMID 40573290, 2025). "For apoptosis, BCL-2 inhibitors such as venetoclax have reshaped standards of care in acute myeloid leukemia (AML) and continue to expand through combination regimens." (PMID 41155529, 2025). "Its mechanistic versatility contrasts with yet complements targeted agents like venetoclax—a clinically validated BCL-2 inhibitor that achieved therapeutic efficacy in acute myeloid leukemia (AML) through selective apoptotic induction." (PMID 40422787, 2025). "Genomes of acute myeloid leukemia (AML) cells resistant to the BCL-2–selective inhibitor venetoclax (VEN) show extensive differential methylation with the activation of the RAS/MAPK pathway, leading to increased stability and higher levels of MCL-1 protein." (PMID 38279330, 2024). "In the second stage, the researchers investigated the effect of ASOs targeting Bcl-2 in acute myeloid leukemia (AML)." (PMID 39272802, 2024). "Venetoclax (ABT‐199) is a potent and selective inhibitor of Bcl‐2, approved for treating chronic lymphocytic leukemia (CLL) and acute myeloid leukemia (AML) in patients with specific genetic profiles indicating Bcl‐2 dependence." (PMID 39239068, 2024). "Chidamide inhibits Myc and BCL2 in acute myeloid leukemia, and its combination with doxorubicin in treating T-cell lymphoma also downregulates BCL2." (PMID 38381215, 2024). "Venetoclax (VEN), an oral BCL2 inhibitor, is approved for use in patients with acute myeloid leukemia (AML)." (PMID 38371152, 2024). "We previously reported that PegC, in combination with the Bcl2 inhibitor venetoclax, inhibits protein synthesis through interference with cap-dependent mRNA translation downstream of mTOR signaling in acute myeloid leukemia (AML)." (PMID 38951899, 2024). "The emergence of resistance to the highly successful BCL2-directed therapy is a major unmet need in acute myeloid leukemia (AML), an aggressive malignancy with poor survival rates." (PMID 37507802, 2023). "Venetoclax (ABT-199), a representative BH3 mimic, is used for chemotherapy of hematologic malignancies including acute myeloid leukemia (AML) that shows high expression of BCL-2." (PMID 36609747, 2023). "The identifying of B-cell lymphoma 2 (Bcl-2) as a therapeutic target has led to a paradigm shift in acute myeloid leukemia (AML) treatment." (PMID 37679782, 2023). "The selective BCL-2 inhibitor venetoclax has proven strong efficacy in many hematological cancers (ex., chronic lymphocytic lymphoma, acute myeloid leukemia, mantle cell lymphoma), which share its dependency on BCL-2 anti-apoptotic signaling." (PMID 36980596, 2023). "The BCL-2 inhibitor Venetoclax is a promising agent for the treatment of acute myeloid leukemia (AML)." (PMID 37726279, 2023). "BCL-2 inhibition using Venetoclax has emerged as a promising therapy in Acute Myeloid Leukaemia (AML), but primary and acquired resistance is a main limitation of this treatment." (PMID 37726279, 2023).